MCL1 (MCL1 apoptosis regulator, BCL2 family member)
Diseases named in the same sentence as MCL1 in open-access papers (continued):
Sharing a sentence is not in itself a finding about the gene and the disease.
prostate carcinoma (continued). "Particularly advanced prostate cancer tissues very often display high Mcl-1 protein levels." (PMID 37173959, 2023). "It was found that IL-6 could inhibit the oncogenic and cell cycle protein A-mediated phosphatidylinositol 3 kinase signaling pathway on prostate cancer cells by inhibiting the anti-apoptotic effect of the gene Mcl-1 after fine expression 26,27." (PMID 37576403, 2023). "Moreover, we demonstrated that deubiquitinase USP9x as a factor regulating Mcl-1 levels in prostate cancer cells, thus limiting cytotoxic response to radiotherapy." (PMID 37173959, 2023). "Moreover, radiotherapy itself was able to regulate Mcl-1 protein stability in prostate cancer cells." (PMID 37173959, 2023). "Finally, we want to point out that our experiments analyzing USP9x-mediated Mcl-1 stability were carried out in two prostate cancer cell lines only." (PMID 37173959, 2023). "In addition, we analyzed how levels of the protective protein Mcl-1 were regulated in prostate cancer cells." (PMID 37173959, 2023). "We, therefore, hypothesized that the deubiquitinase USP9x contributes to prostate cancer progression by controlling Mcl-1 protein stability." (PMID 37173959, 2023). "The moderate and highly significant positive correlation between Mcl-1 and USP9x immunoreactivity (Spearman’s r = 0.560, p = 0.000043; Pearson’s r = 0.510, p = 0.00025) proposed an interrelation between the anti-apoptotic protein Mcl-1 and the deubiquitylating enzyme USP9x in prostate cancer." (PMID 37173959, 2023). "Although not all prostate cancer cells might use USP9x to stabilize Mcl-1, USP9x might account for elevated Mcl-1 levels, particularly in advanced prostate cancer." (PMID 37173959, 2023). "Both can contribute to the changes of Mcl-1 protein levels and may vary in the extent of contribution between different cell lines as well as the stages during prostate cancer progression." (PMID 37173959, 2023). "We provide evidence that transcriptional upregulation of the MCL1 gene is not the cause of elevated Mcl-1 protein levels in prostate cancer." (PMID 37173959, 2023). "Bcl-2 and Mcl-1 were important targets of STAT signaling in prostate cancer." (PMID 34976194, 2022). "Additionally, the stem extract showed an interesting ability to reduce the expression of anti-apoptotic proteins (Bcl-xL and Mcl-1) and increase the expression of pro-apoptotic proteins (caspase-3 and Noxa) in prostate cancer cells." (PMID 35209099, 2022). "One other report on prostate cancer cells receiving combined treatment of ibuprofen and epigallocatechin-3-gallate, reported changes in alternative splicing, in particular promoting the shorter and proapoptotic BCL-X (S) or MCL-1(S) variants." (PMID 33315986, 2020). "Sabutoclax, another BH3-mimetic targeting MCL1, could sensitize prostate cancer cells to IL-24 mediated cytotoxicity." (PMID 25749045, 2015). "Demethylation of these promoters leads to the decrease in expression of TRIM68 and PGK1 in prostate cancer cells, whilst methylation of the promoter of miRNA-29a led to increased expression of Myeloid cell leukemia sequence 1 (Mcl-1) which blocks apoptosis and supports cell survival in lymphoma." (PMID 25647662, 2015). "In order to assess expression of MCL1 in prostatic tissue and to validate MCL1 as a potential target for treatment of PCa we performed immunohistochemistry on tissue specimens from treatment-naïve prostate cancer (tnPCa) patients who underwent radical prostatectomy." (PMID 25749045, 2015). "However, anti-apoptotic Bcl-2 family proteins such as Bcl-2, Bcl-xL, or Mcl-1 prevent the PTP opening and are associated with treatment resistance and progression in many types of cancer, including prostate cancer." (PMID 26252009, 2015). "Actually, this kinase was involved in Mcl-1 regulation in a model of prostate carcinoma cells." (PMID 25627260, 2015).
prostate carcinoma (continued). "In summary, we developed a dynamic network model of signaling pathways that control apoptosis in prostate cancer cells to study the role of psychological stress on prostate cancer therapy, and justified the role of Mcl-1 stabilization in anti-apoptotic effects of emotional stress." (PMID 24339759, 2013). "Also, apoptosis in C42Luc cells was decreased by knocking down expression of BIM, identifying BIM as important regulator of apoptosis downstream of MCL-1 in C42Luc prostate cancer cells." (PMID 24040284, 2013). "To further investigate the mechanisms of TRAIL sensitization by GSK-3 inhibition, we employed PPC-1 prostate cancer cell overexpressing Bcl-2, Bcl-XL, and Mcl-1 to inhibit the mitochondrial pathway, or cytokine response modifier A (CrmA) to inhibit the death receptor pathway of caspase activation." (PMID 22829912, 2012). "Moreover, radiotherapy itself affected Mcl-1 protein turnover in prostate cancer cells." (PMID 37173959, 2023). "Thus, the downregulation of Mcl-1 sensitized prostate cancer cells to ionizing radiation." (PMID 37173959, 2023). "Interestingly, we detected an association between patient survival and gene expression of USP9X only, but not of HUWE1, BTRC, and FBXW7, even though all gene products are able to interact with Mcl-1, further emphasizing the role of the deubiquitinase in prostate cancer progression." (PMID 37173959, 2023). "Additionally, direct and indirect knockdown of MCL-1 has been shown to sensitize prostate cancer cells to anti-mitotic agents, including docetaxel, suggesting that MCL-1 targeting may also synergize with chemotherapy." (PMID 35008216, 2021). "We show here in prostate cancer cells that increased NOXA, mediated by kinase inhibitor activation of an integrated stress response, drives the degradation of MCL1, and identify the mitochondria-associated ubiquitin ligase MARCH5 as the primary mediator of this NOXA-dependent MCL1 degradation." (PMID 32484436, 2020). "Autocrine IL-6-induced Mcl-1 could protect prostate cancer cells from apoptosis." (PMID 21880146, 2011). "To examine the interaction between the anti-apoptotic protein Mcl-1 and USP9x in more detail, we employed LNCaP and PC3 prostate cancer cell lines." (PMID 37173959, 2023). "PGG inhibited STAT3 Tyr705 phosphorylation in the prostate cancer DU145 cell line, thereby downregulating STAT3 transcriptional targets, such as Bcl-XL and Mcl-1, which decreased cell viability and increased caspase-mediated apoptosis." (PMID 37375411, 2023). "We now verified the cooperative protection from apoptosis by Bcl-2, Bcl-xL, and Mcl-1 in LNCaP and PC3 prostate cancer cells." (PMID 37173959, 2023). "Recently, other SH2 domain inhibitors (323-1 and 323-2) have been developed and lead to the downregulation of STAT3 downstream genes, like the MCL1 apoptosis regulator (MCL1) and cyclin D1 (CCND1), in DU145 prostate cancer cells." (PMID 38067351, 2023). "In particular, we examined the posttranslational regulation of Mcl-1 protein levels by USP9x and the relevance of this mechanism for cell survival in human LNCaP and PC3 prostate cancer cells." (PMID 37173959, 2023). "After Mcl-1 knockdown, we detected a significant increase in radiation-induced apoptosis and cell death in both LNCaP and PC3 prostate cancer cells." (PMID 37173959, 2023). "In prostate cancer cells, the transcription factors β-catenin and hypoxia-inducible factor (HIF)-1α were able to upregulate MCL1 gene expression, while specific miRNAs were able to downregulate MCL1 mRNA and thus also Mcl-1 protein levels." (PMID 37173959, 2023). "Mcl-1 downregulation by miRNA-3614-5p induces the activation of caspase 3 and PARP in prostate cancer cells." (PMID 35457012, 2022). "Regulation of Mcl-1 expression by miRNA-3614-5p was further investigated by immunoblotting analysis in human PC3 and 22Rv1 prostate cancer cells." (PMID 35457012, 2022).
prostate carcinoma (continued). "PDGF-BB has been shown to upregulate the Bcl-2 family member named Myeloid Cell Leukemia-1 (Mcl-1) by forming a transcription complex between β-catenin and HIF-1α in prostate cancer cells." (PMID 35158804, 2022). "Consistently, the MCL‐1 inhibitors S63845, UMI77 and AZD5991 efficiently eliminated those senescent prostate cancer cells." (PMID 36065138, 2022). "A number of immunohistological studies have shown high levels of MCL-1 and BCL-XL in prostate cancer, but BCL-2 appears to be expressed at lower levels, with more interstudy variability." (PMID 35008216, 2021). "The upregulation of MCL-1 by BH3-mimetics was not limited to HeLa cells, since it was also observed in IMR90 lung fibroblasts and CWR-R1 prostate cancer cells." (PMID 34772930, 2021). "In prostate cancer, the BH3-mimetic sabutoclax blocks the prosurvival BCL2 family member, myeloid cell leukemia-1 (MCL1), and activates the autophagic process to facilitate the induction of apoptosis mediated by NOXA and BIM." (PMID 34830777, 2021). "In contrast to hematological malignancies, solid tumors, including prostate cancer, are more dependent on BCL-XL and MCL-1 for cell survival." (PMID 35008216, 2021). "In prostate cancer cell lines, the proteins of BCL-2 family MCL1, BAK, BAD and BIM can be regulated by signal transduction pathways amenable for pharmacological targeting." (PMID 33668112, 2021). "Our mechanistic studies suggest that Bcl‐xL, Bim, CHK1, c‐Myc, Mcl‐1, RRM1, RRM2 and Wee1 play a role in the antitumour activity of CUDC‐907 against prostate cancer." (PMID 32459381, 2020). "Our functional studies confirm that down‐regulation of Bcl‐xL and Mcl‐1 and up‐regulation of Bim contribute to the antitumour activity of CUDC‐907 against prostate cancer cells." (PMID 32459381, 2020). "Increased MCL-1 expression and BAD phosphorylation were identified as target molecules responsible for apoptosis inhibition in prostate cancer cells by ADRB2/PKA pathway, whereas the effectors responsible for accelerated migration await further investigation." (PMID 30871232, 2019). "Fourth, in a broader context, the effects of propranolol on apoptosis in prostate cancer cells will also depend on other BCL family proteins beside BAD and MCL-1." (PMID 30871232, 2019). "In prostate cancer cells, platelet-derived growth factor (PDGF) has been shown to induce MCL-1 expression." (PMID 26035829, 2015). "For example, the stress protein BAG3 can stabilize Mcl-1, resulting in increasing ABT-737 resistance in several cancer types including prostate cancers." (PMID 25811469, 2015). "The downstream survival signaling network was mediated by NF-κB and Mcl-1 and EMT was driven by receptor activator of NF-κB ligand (RANKL), at the single cell level in clinical prostate cancer specimens and the xenograft model." (PMID 22205960, 2011). "Current evidence supports MCL1 as a promising antiviral target, but its regulation by testosterone remains largely inferred from non-infectious models like prostate cancer." (PMID 40872527, 2025). "Indeed, MYC, MCL-1, and BCL-2 are important oncoproteins in both AR-driven and AR-independent prostate cancer." (PMID 39117800, 2024). "The stability of Mcl-1 reflected Mcl-1 protein levels in LNCaP and PC3 prostate cancer cells." (PMID 37173959, 2023). "Targeting Mcl-1 or USP9x improved the response of LNCaP and PC3 cells to radiotherapy and might prove beneficial for prostate cancer patients receiving radiotherapy." (PMID 37173959, 2023). "Therefore, we evaluated cell death following Mcl-1 mRNA silencing in both LNCaP and PC3 prostate cancer cells, using specific siRNA pools at a concentration between 10 nM and 100 nM." (PMID 37173959, 2023). "Although MCL1 expression did not affect the survival of patients with prostate cancer, expression data suggests a more prominent role for the deubiquitinase USP9x." (PMID 37173959, 2023).
prostate carcinoma (continued). "A possible interaction between Mcl-1 and USP9x was examined in LNCaP and PC3 prostate cancer cells." (PMID 37173959, 2023). "In accordance with these observations, we detected no change in MCL1 gene expression between normal prostate tissue and prostate cancer tissue, but we observed upregulated Mcl-1 protein levels during prostate cancer progression." (PMID 37173959, 2023). "For the next set of experiments, we transfected prostate cancer cells with 50 nM Mcl-1 or non-targeting (nt) control siRNA 24 h prior to irradiation with 10 Gy." (PMID 37173959, 2023). "Significantly, MARCH5 depletion prevented the decrease in MCL1 by erlotinib and cabozantinib (C-MET/VEGFR2 inhibitor) in LNCaP cells, and in other prostate cancer cells (PC3 and DU145 cells), indicating that the decreases in MCL1 by these kinase inhibitors are mediated by MARCH5." (PMID 32484436, 2020). "The effects of CUDC‐907 on Bcl‐xL, Bim and Mcl‐1 in prostate cancer cells are not surprising because CUDC‐907 inhibits both PI3K and HDACs." (PMID 32459381, 2020). "Activation of β2-AR signaling induces phosphorylation of PKA substrates CREB, vasodilator-stimulated phosphoprotein (VASP), Bcl-2 antagonist of cell death (BAD) and increases expression of myeloid cell leukemia 1 (MCL-1), leading to inhibition of apoptosis in prostate cancer." (PMID 33419318, 2020). "Similarly, cryptocaryone also reportedly induced apoptosis in human prostate cancer PC3 cells in terms of the subG1 accumulation, cleavage of caspase-8 and 3, death receptor DR5 accumulation on membranes, and up-regulation of Mcl-1 expression." (PMID 26955958, 2016). "The role of Mcl-1 in mediating resistance to chemotherapy-induced DNA damage in prostate cancer (PCa) is not known." (PMID 26425662, 2015). "Prostate cancer cells commonly express three anti-apoptotic Bcl proteins: BCL-XL, BCL-2, and MCL-1." (PMID 24040284, 2013). "Moreover, we did not examine additional factors regulating Mcl-1 stability in either cell lines or tissue samples during prostate cancer progression." (PMID 37173959, 2023). "Furthermore, several receptor tyrosine kinase inhibitors, including erlotinib, lapatinib, cabozantinib, and sorafenib have been shown to increase MCL-1 degradation, resulting in robust apoptotic cell death when combined with ABT-737 in prostate cancer cells, both in vitro and in vivo." (PMID 35008216, 2021). "The expression of both pro-apoptotic (BAX,BIK, and BAD) and anti-apoptotic genes(MCL-1 and BCL-XL) was not affected byBAP1-knockdown in prostate cancer cells." (PMID 32422649, 2020).
hepatocellular carcinoma (92 papers, 2006 to 2025). A malignant tumor that arises from hepatocytes. "Similarly, inhibition of MCL-1 by miR-101-3p has been implicated in the apoptosis-inducing effect of anti-cancer drug doxorubicin in hepatocellular carcinoma." (PMID 31864341, 2019). "Navitoclax increases the mRNA and protein levels of Mcl‐1 in hepatoma cells, contributing to resistance against the drug." (PMID 39428564, 2024). "Mcl-1, an antiapoptotic protein overexpressed in many tumours, including hepatocellular carcinoma (HCC), represents a promising target for cancer treatment." (PMID 37663116, 2023). "Beclin-1 is one of the key proteins of autophagy progress Research has shown that sorafenib and its derivative sc-59 induce hepatoma autophagy through the SHP-1/STAT3/MCL-1/Beclin-1 pathway." (PMID 37181755, 2023). "Studies have reported that, as an important anti-apoptotic protein, Mcl-1 is also over-expressed in hepatocellular carcinoma, which is one of the important factors of HCC drug resistance." (PMID 36386146, 2022). "MCL-1 knockdown or specific inhibitors of S63845 or A-1210477 significantly inhibited hepatocellular carcinoma spheroid cell formation and triggered apoptotic signals." (PMID 33883020, 2021). "To date, except for MCL1 which has been proven by us and other literature studying hepatocellular carcinoma, among the validated miR-26a targets, HMGA1, PTEN, EZH2, MITF, DNMT3B, TGF-beta, and Ezh2 have been demonstrated to regulate chemoresistance." (PMID 33816494, 2021). "Since a novel BH3-mimetic, A-1210477, highly specific for MCL-1 has been recently described, we tested it, in order to deplete MCL-1 levels in hepatoma cells and combined with BCL-xL reduction using A-1331852." (PMID 32024199, 2020). "Repression of GALNT10 decreases the expression of Mcl-1 and Bcl-2, increasing sorafenib and doxorubicin resistance of hepatoma cells." (PMID 32182776, 2020). "For example, miR-125b was found to sensitize hepatocellular carcinoma (HCC) cells to chemotherapeutic treatment by directly targeting MCL-1, BCL-W and indirectly targeting BCL-XL." (PMID 29570632, 2018). "For instance, microRNA-193b enhances the cytotoxicity of cisplatin to hepatocellular carcinoma cells by targeting Mcl-1." (PMID 28659182, 2017). "(A-C) Correlation analysis of miR-500a-3p expression and Bcl-2, Bcl-xL and MCL1 mRNA expression levels in 8 fresh human hepatocellular carcinoma tissues." (PMID 28750679, 2017). "In line with this, Bcl-xL inactivation (ABT-737) in combination with sorafenib, that down-regulates Mcl-1 expression specifically in tumor cells, efficiently induced cell death in hepatoma cells." (PMID 26811497, 2016). "As expected, reconstitution of Mcl-1 expression robustly reduced the cell apoptosis triggered by ψ-Bufarenogin, suggesting that ψ-Bufarenogin facilitates the apoptosis of hepatoma cells through downregulating Mcl-1 expression." (PMID 25890498, 2015). "Western blot analysis showed that MCL1 was overexpressed in two human hepatocellular carcinoma cell lines, while SIRT1 was elevated in all the examined cell lines." (PMID 25888625, 2015). "Previous studies from hepatocellular carcinomas have suggested that MCL-1 and FOS were regulated by miR-101." (PMID 25153722, 2014). "Studies targeting Mcl-1 via antisense therapy have also shown to chemosensitize hepatocellular carcinoma cells in vitro." (PMID 25409302, 2014). "In this study we assessed the expression of TRAIL receptors, caspase-8, Bcl-xL and Mcl-1 in 157 patients with hepatocellular carcinoma and normal liver tissue using tissue microarrays, and correlated the expression with clinico-pathological parameters." (PMID 24209510, 2013). "In this study, we investigated the potentially synergistic abilities of ABT-737 in combination with Celastrol in human hepatocellular carcinoma cell lines, in which mostly harbor high level of Mcl-1 protein expression." (PMID 23284992, 2012).